HMGB1 (high mobility group box 1)
Diseases named in the same sentence as HMGB1 in open-access papers (continued):
Sharing a sentence is not in itself a finding about the gene and the disease.
endometriosis (continued). "HMGB-1 expression was significantly increased in secretory phase of endometriosis group, comparing to the controls." (PMID 26872033, 2016). "In preceding immunohistochemistry experiments using paraffin-block sections from endometriosis (N = 33) and control (N = 27) group, retrospectively, HMGB-1 expression was shown in both epithelial and stromal cell." (PMID 26872033, 2016). "In endometrium from patients with endometriosis, significantly increased HMGB-1 expression was detected in the early and mid-secretory phase as compared to the control." (PMID 26872033, 2016). "Comparing to the controls, significantly increased expression of HMGB-1 was shown at early and mid-secretory phase in patients with endometriosis." (PMID 26872033, 2016). "Immunohistochemistry showed presence of HMGB-1 in human endometrial cells and significantly increased HMGB-1 expression during secretory phase in endometriosis group compared to the normal controls, additionally." (PMID 26872033, 2016). "Increased oxidative stress may induce the danger signal such as HMGB-1 in granulosa cells and eventually change the follicular environment of patients with endometriosis." (PMID 41226929, 2025). "High mobility group box-1 (HMGB1) also plays a critical role in endometriosis." (PMID 40909174, 2025). "They discovered a positive correlation between their levels with HMGB1 expression, suggesting that HMGB1 may play a role in the pathogenesis of endometriosis by affecting glycolysis." (PMID 37691930, 2023). "not only localized HMGB1 in endometriosis patients but also found that its circulating levels were higher in these patients than in women without the disease, indicating its potential as a biomarker for detecting endometriosis." (PMID 37691930, 2023). "Mechanistically, lactate induced H3K18lac to promote the expression of high-mobility group box 1 (HMGB1) in endometriosis, and HMGB1 knockdown significantly reduced the cell proliferation, migration, and invasion of the lactate-treated cells through the phosphorylation of AKT." (PMID 37945340, 2023). "HMGB-1 may contribute to the development of endometriosis in part by regulating the inflammatory response and autophagy." (PMID 37691930, 2023). "In the present study, we demonstrated that the lactate could induce histone lactylation to promote endometriosis progression by upregulating the expression of HMGB1, which may provide a novel target for the prevention and treatment of endometriosis." (PMID 37945340, 2023). "Therefore, more research is necessary to determine the viability of HMGB1 as a biomarker for endometriosis." (PMID 37691930, 2023). "We carried out rescue experiments to investigate the lactate/HMGB1 axis in endometriosis." (PMID 37945340, 2023). "In conclusion, lactate could induce histone lactylation to promote endometriosis progression by upregulating the expression of HMGB1, which may provide a novel target for the prevention and treatment of endometriosis." (PMID 37945340, 2023). "In the present study, we demostrated that lactate induced histone lactylation to promote endometriosis progression through upregulating the expression of HMGB1, which may provide a novel target for endometriosis treatment in the future." (PMID 37945340, 2023). "The lactate may induce histone lactylation to promote endometriosis progression through upregulating the expression of HMGB1." (PMID 37945340, 2023). "High plasma HMGB1 has been recognized as a biomarker for endometriosis." (PMID 37945340, 2023). "However, the potential relationship between HMGB-1 and autophagy in endometriosis remains uninvestigated." (PMID 33815277, 2021). "HMGB-1 might contribute to the development of endometriosis in part through regulating inflammatory response and autophagy." (PMID 33815277, 2021).
endometriosis (continued). "In 2016, for the first time, Bo and colleagues have demonstrated that inhibiting HMGB-1 suppresses the proliferation of HESCs, indicating that targeting HMGB-1 might be a strategy for endometriosis therapy." (PMID 33815277, 2021). "Therefore, to confirm the regulatory role of HMGB-1 in autophagy during endometriosis, hypoxia treatment was used to induce autophagy in HESCs." (PMID 33815277, 2021). "HMGB-1 is commonly used as an admissible biomarker for endometriosis." (PMID 33815277, 2021). "Hence, HMGB-1 may play an essential role in the pathogenesis of endometriosis by regulating inflammation." (PMID 36865552, 2023). "However, it is still unknown how inhibiting HMGB-1 could exert beneficial effects against endometriosis." (PMID 33815277, 2021). "Our results revealed that HMGB-1 was upregulated in ectopic endometrium, which was also positively correlated with inflammatory cytokines IL-6, TNF-α, and IL-1β, as well as autophagy-related protein beclin-1, suggesting that HMGB-1 might be involved in endometriosis." (PMID 33815277, 2021). "This study aimed to demonstrate that HMGB-1 and its receptors, TLR4 and RAGE, play important roles in the changes in the follicular environment in infertile patients with endometriosis." (PMID 41226929, 2025). "SASP gene products identified by RNAseq include many inflammatory biomarkers that have been historically analyzed in endometriosis, including IL-1β, IL-6, IL-8, CCL5, TNF-α, CCL2, MMP3, HMGB1, p16, and p21." (PMID 38879630, 2024). "The preoperation plasma HMGB1, OPN and HA levels in women with endometriosis were significantly elevated when compared with that in controls (all p ≤ 0.0012)." (PMID 31239500, 2019). "In summary, plasma HMGB1, OPN, and HA are promising admissible biomarkers for diagnosing endometriosis." (PMID 31239500, 2019). "Taken together, it can be concluded that plasma HMGB1, OPN, and HA levels are all admissible biomarkers for endometriosis." (PMID 31239500, 2019). "Through this integrated approach, we identified plasma HMGB1, OPN and HA as promising and admissible biomarkers for endometriosis." (PMID 31239500, 2019). "Through this integrated approach, we identified plasma HMGB1, OPN and HA as promising admissible biomarkers for endometriosis." (PMID 31239500, 2019). "Researchers have found that HMGB1 is present in the endometrial cells of women with endometriosis, compared to those who do not." (PMID 37691930, 2023). "In addition, the HMGB-1/TLR4/NF-κB axis can also induce the proliferation and invasion of endometriotic cells and contribute to endometriosis-induced pain 52-54." (PMID 35864971, 2022). "Thus, it can be concluded that plasma HMGB1, OPN, and HA levels are all biomarker candidates for endometriosis." (PMID 31239500, 2019). "Since fibrosis is the end result of lesional development, we chose high mobility group box 1 (HMGB1), osteopontin (OPN), and hyaluronic acid (HA), all three of them have been well documented to be involved in endometriosis and fibrosis, as potential biomarkers." (PMID 31239500, 2019). "However, it was also observed that HMGB1 was not significantly upregulated in patients with severe endometriosis." (PMID 37691930, 2023). "Additionally, although it was not the primary purpose of this study, we have performed immunohistochemistry to identify expression of HMGB-1 in endometrial samples from patients with and without endometriosis." (PMID 26872033, 2016). "Because of the sensitivity of HMGB-1 to the oxidation-reduction state of the surrounding environment, HMGB-1-mediated NF-κB signaling may be the predominant mechanism during early inflammation of the endometrium in patients with endometriosis." (PMID 26872033, 2016). "However, high level of HMGB1 levels may result in female reproductive disorders, including recurrent spontaneous abortion (RSA), gestational diabetes mellitus (GDM), preterm birth (PTB), preeclampsia (PE), polycystic ovary syndrome (PCOS), and endometriosis." (PMID 37691930, 2023).
endometriosis (continued). "To confirm the results we found in mouse, we measured plasma levels of HMGB1, OPN, and HA in 30 patients with ovarian endometriomas (OE) and 20 women without endometriosis." (PMID 31239500, 2019).
nasopharyngeal carcinoma (20 papers, 2012 to 2025). A carcinoma arising from the nasopharyngeal epithelium. "Furthermore, in nasopharyngeal carcinoma cells, endogenous HMGB1 expression was associated with invasiveness." (PMID 25622595, 2015). "In nasopharyngeal carcinoma, HMGB1 directly interacts with Ku70, a critical NHEJ factor, which promotes the DNA-binding activity of Ku70 and enhances the efficiency of the NHEJ repair pathway, contributing to resistance to ionizing radiation and cisplatin." (PMID 41465435, 2025). "Knockdown of HMGB1 in nasopharyngeal carcinoma cells inhibits the activation of the HMGB1/RAGE pathway, downregulating the expression of p-ERK1/2 and reducing the migration and invasion capabilities of cancer cells." (PMID 38529373, 2024). "Two articles have demonstrated that the HMGB1/RAGE axis can promote proliferation in nasopharyngeal carcinoma (NPC)." (PMID 38529373, 2024). "Previous studies on nasopharyngeal cancer found that patients with high expression of HMGB1 had later tumor stage and poor prognosis after chemo-radiotherapy." (PMID 36260180, 2022). "In this study, we demonstrated that the lncRNA MIAT/HMGB1 axis is highly upregulated in cisplatin-resistant nasopharyngeal carcinoma cell lines." (PMID 34094941, 2021). "Although members of the high-mobility group box family have been implicated in carcinogenesis (e.g., high expression of HMGB1 in human nasopharyngeal carcinoma) and autoinflammatory diseases, no published literature exists on diseases or disorders specifically associated with HMGB1P23." (PMID 40160448, 2025). "Accordingly, HMGB1 knockout or pharmacological inhibition with glycyrrhizin impairs NHEJ and re-sensitizes resistant nasopharyngeal cancer cells to both ionizing radiation and cisplatin." (PMID 41465435, 2025). "What’s more, it was reported that HMGB1-RAGE signalling triggered activation of several key cell signalling pathways, such as MAPK, NF-κB, and Rac/Cdc42 in nasopharyngeal carcinoma." (PMID 34933679, 2021). "For instance, ATP is considered as a promising adjuvant in the treatment of nasopharyngeal carcinoma (NPC) and HMGB1 is described as a target in some inflammatory diseases." (PMID 34201190, 2021). "In nasopharyngeal carcinoma (NPC), the same family of HMGB2, high mobility group box 1 (HMGB1), the direct target of dead box helicase 5 (DDX5), is upregulated by the NAT10-mediated ac4C modification of DDX5, which inhibits the T-cell immunity of CD4 + and CD8 + T cells and promotes NPC progression." (PMID 41316475, 2025). "For instance, in nasopharyngeal carcinoma, HMGB1 enhances the non-homologous end-joining (NHEJ) DNA repair pathway through interaction with Ku70, contributing to resistance to both radiotherapy and cisplatin." (PMID 40969278, 2025). "In addition, inhibition of autophagy mediated by HMGB1, LMP1, or NEDD8 also promoted treatment responses to IR in ESCC, nasopharyngeal carcinoma and oral squamous cell carcinoma, respectively." (PMID 38783335, 2024). "HMGB1 has been shown to be an independent prognostic factor for patients with squamouscell carcinoma of the head and neck, and its overexpression also plays a role in the progression of nasopharyngeal carcinoma (NPC) and is correlated with a poor clinical outcome." (PMID 23866030, 2013).
thrombosis (20 papers, 2013 to 2025). "Level of HMGB1/sRAGE increases in plasma and serum of patients with inflammatory diseases associated with sepsis or thrombosis." (PMID 30923525, 2019). "HMGB1 was associated with thrombosis in patients with AF via the MyD88/NFκB pathway after adjustment for cardiac and extra cardiac inflammation variables." (PMID 29595637, 2018). "We confirm here that HMGB1 content in PLTs and in their derived MV in high-risk thrombosis patients is increased in comparison with PLTs from HVs of a younger age group and that treatment with aspirin reduces HMGB1 expression in PLTs and in PLT-derived MV." (PMID 29375570, 2017). "Levels of HMGB1 increase in plasma and serum of patients with inflammatory diseases associated with sepsis or thrombosis." (PMID 29375570, 2017). "We hypothesize that HMGB1 and its downstream factors are associated with thrombosis in atrial fibrillation (AF)." (PMID 29595637, 2018). "While a critical role for platelet-derived HMGB1 has been established in coronary thrombi, experimental trauma/hemorrhagic shock, and venous thrombosis, the present study confirms its significance in the PTS model." (PMID 39910417, 2025). "In contrast to ADAMTS-13, HMGB1 has been shown in an animal model of deep vein thrombosis to induce pro-thrombotic neutrophil extracellular trap formation and in vivo/in vitro platelet aggregation." (PMID 37863934, 2023). "Platelets were identified as the main source of NET-inducing HMGB1 in stroke patients, and another group demonstrated, that murine platelets promote arterial thrombosis via TLR4-dependent NETosis induction." (PMID 35979369, 2022). "We also addresses the function of peptidylarginine deiminase 4 with respect to the interplay with HMGB1 in NET-induced thrombosis." (PMID 32731558, 2020). "Utilizing a transgenic mouse lacking HMGB1 specifically from platelets and megakaryocytes we now demonstrate the specific role of platelet-derived HMGB1 in acute and subacute/chronic venous thrombosis." (PMID 29391442, 2018). "Furthermore, HMGB1 triggered the formation of prothrombotic NETs in an animal model of deep venous thrombosis, a process mediated by the receptor for advanced glycation end products (RAGE)." (PMID 39910417, 2025). "HMGB1 also promotes prothrombotic NET formation in deep venous thrombosis." (PMID 38716542, 2024). "Extruded HMGB1 in turn, induces platelet activation, thrombosis and further aggravates NETosis." (PMID 37153586, 2023). "Beyond NETs as a treatment target, platelets may promote NET formation, and platelet-derived HMGB1 was repeatedly identified as key molecule in venous, as well as arterial thrombosis." (PMID 35979369, 2022). "Interestingly, investigating a murine model of deep vein thrombosis revealed that the pro-thrombotic effect of HMGB1 was mediated through the release of extracellular DNA during NET formation." (PMID 35741047, 2022). "Emerging evidences indicate that HMGB1 plays a critical role in thrombosis-related diseases." (PMID 32731558, 2020). "Interestingly, promotion of prothrombotic NET formation by administration of disulfide HMGB1 was observed in venous thrombosis, which was mediated by RAGE." (PMID 32731558, 2020). "Moreover, HMGB1 expression on the surface of circulating platelets was markedly upregulated in patients with systemic sclerosis, trauma and deep vein thrombosis." (PMID 32731558, 2020). "HMGB-1-mediated PMN activation subsequently contributes to microvascular thrombosis and NETosis." (PMID 27446071, 2016). "Moreover, platelet HMGB1 was demonstrated to promote venous thrombosis in mice." (PMID 35979369, 2022). "Moreover, it has been demonstrated that platelet activation increases RAGE surface expression and that HMGB1 may represent a master regulator of the prothrombotic cascade involved in the pathogenesis of deep venous thrombosis." (PMID 30923525, 2019).
thrombosis (continued). "To investigate whether aspirin could regulate HMGB1 expression and secretion in vivo, we studied the content of HMGB1 in PLTs, MV, plasma, and in sera from high-risk thrombosis patients treated or not with aspirin (groups 3 and 4)." (PMID 29375570, 2017). "HMGB1 is a DNA-binding protein that has procoagulant and proinflammatory functions and mediates NET formation in venous thrombosis, trauma, and cancer." (PMID 35358095, 2022). "This pro-thrombotic effect was further supported and enhanced by neutrophil recruitment and NET formation, indicating that the interplay between platelet-derived HMGB1 and NET release has a crucial contribution to deep vein thrombosis in mice." (PMID 35741047, 2022). "Additionally, platelet HMGB1 was found to enhance DVT and increase the formation of neutrophil extracellular traps (NETs), although the role of HMGB1 induced NET release in thrombosis remains unexplored." (PMID 29391442, 2018). "HMGB1 is a highly conserved, non-histone chromosomal protein that has pro-inflammatory and pro-coagulant functions and mediates NET formation in venous thrombosis and tumor." (PMID 37153586, 2023). "In APS patients with recurrent thrombosis, a tendency to have elevated HMGB1 serum levels has been highlighted, compared to APS patients without recurrent thrombosis, although this result does not reach statistical significance." (PMID 30923525, 2019).